BATF3 (basic leucine zipper ATF-like transcription factor 3)
Diseases named in the same sentence as BATF3 in open-access papers (continued):
Sharing a sentence is not in itself a finding about the gene and the disease.
tumor (continued). "STING activation initiates a type I interferon (IFN)-driven pro-inflammatory program that stimulates basic leucine zipper transcriptional factor ATF-like 3 (BATF3)-dependent dendritic cell (DC) cross-presentation and promotes CD8+ T cell-mediated anti-tumor immune responses." (PMID 34298601, 2021). "Batf3-dependent type 1 conventional DCs plays a critical role in anti-tumor immunity, including CD8+ DCs (non-migrating resident DCs) and CD8- DCs (migratory DCs)." (PMID 34660305, 2021). "For tumor immunity, cross-priming by type 1 classical dendritic cell (cDC1) subsets, whose development and/or function depends on basic leucine zipper ATF-like transcription factor 3 (Batf3) transcription, is necessary for optimal generation of Trm cells." (PMID 35096624, 2021). "CD8α+/XCR1+ cDC1 was found to fail in cross-presenting to CD8+ T cells and tumor rejection in the absence of WDFY4 gene, but these mice had normal lymphoid and non-lymphoid cDC1 populations compared to BATF3-deficient mice." (PMID 34884995, 2021). "Treatment of Batf3−/− mice lacking cross-presenting DCs required for CD8+ T cell priming extended survival of tumor-bearing animals, but none rejected their tumors." (PMID 34818534, 2021). "Altogether, they indicate that Mmp2 signals through both BATF3+ DCs and T cells to enhance tumor growth, and in the absence of Mmp2, this dependency is lost." (PMID 34032639, 2021). "In summary, our results demonstrated that LINC01638/miR-523-5p/BATF3 axis plays a crucial function in initiating LSCC development and may be a potential target for tumor therapy." (PMID 33714208, 2021). "To test whether the effect of DNGR-1 on tumor growth and cDC1 infiltration was directly dependent on cDC1s, we treated WT or Batf3–/– mice with FL and inoculated them subcutaneously with B16F10 tumor cells." (PMID 33980589, 2021). "In contrast, CD40LG is moderately correlated with PAX5 (B cells, r = 0.45 and 0.46 in normal and tumor tissues, respectively), but not BATF3 (dendritic cells)." (PMID 34758832, 2021). "In both mice and humans, Batf3-dependent conventional type 1 DC (cDC1) are purported to be the primary DC subpopulation responsible for the cross-priming of tumor-specific CD8+ T cells as well as their recruitment to and activation within the tumor." (PMID 32841222, 2020). "We show that the mechanistic basis for the synergy was not G007-LK-mediated enhanced release of the BATF3-lineage DC-attracting chemokine CCL4 or increased tumor infiltration by CD8+ T cells." (PMID 32332858, 2020). "Further, CD103+ DCs are a distinct DC population that is uniquely dependent on IRF8 and Batf3 transcription factors and predominantly expresses CCR7 in human tumors, expression of which was used as a molecular proxy for CD103+ DCs in clinical tumor gene expression data sets." (PMID 32759497, 2020). "Repeat irradiation at doses that induce optimal cytosolic DNA accumulation amplifies IFN-β production, resulting in recruitment and activation of cDC1s, also known as Batf3-dependent DCs, which are essential for priming of CD8+ T cells that mediate systemic tumor rejection (the abscopal effect)." (PMID 32894202, 2020). "Although this implicates some BATF3-dependent function in cDC1s that is important for tumour rejection but independent of cross-presentation, the exact mechanisms are not fully understood." (PMID 31776331, 2019). "In contrast, BATF3 DC migration and T cell priming is not impacted when mice are inoculated with otherwise identical tumor lines expressing wild type β‐catenin." (PMID 31355495, 2019). "CD103+CD11b- DCs require the basic leucine zipper transcription factor ATF-like 3 (BATF3) and interferon regulatory factor 8 (IRF8) for their development and are equipped to cross-present viral, tumor, and self-antigens; the functional human equivalent of CD103+CD11b- DCs is the CD141hi DC subset." (PMID 31188899, 2019).
tumor (continued). "Batf3 knockout mice lack cDC1 cells but not other APCs and display impaired anti-tumor immunity in several models." (PMID 31143179, 2019). "Furthermore, the basic leucine zipper ATF-like transcription factor 3 (BATF3)-dependent DC subset has been recently shown to be essential for the cross-priming of CD8+ T cells, which are key effectors in anti-tumor immunity." (PMID 30115069, 2018). "The results showed that BATF3 expression in tumor tissues was significantly (P < 0.05) higher than distant normal tissues." (PMID 29661228, 2018). "We found GMPs, MDPs, and CDPs from tumor-bearing mice failed to upregulate proteins indicative of the cDC program (e.g., Irf8, Zbtb46, Cd209a, Spib, Batf3, and Bcl11a)." (PMID 29593283, 2018). "First, we observed that tumor growth of PyMT-mCh-OVA, a variant of PyMT-B6 expressing antigenic mCherry and ovalbumin, was restrained in wild-type, but not in BATF3−/− mice." (PMID 29593283, 2018). "Consistent with the proposed regulation of BATF3 and CRC cell proliferation by miR-760, expression patterns of BATF3 and Ki67 in SW620-miR-760 tumors were similar to the in vitro results, supporting the tumor suppressor function of miR-760 in CRC tumorigenesis." (PMID 29661228, 2018). "In addition, Batf3-dependent DCs are crucial for reactivation of circulating CD8+ T-cell memory, inducing anti-tumour immunity." (PMID 28714465, 2017). "Unlike their wild-type controls, Batf3−/− mice failed to reject syngeneic fibrosarcomas, did not develop tumor-specific CTLs, and showed reduced numbers of tumor-infiltrating CD8+ T cells." (PMID 26042126, 2015). "Indeed, Batf3−/− mice are unable to reject highly immunogenic tumors due to defective cross-presentation by Batf3−/− DC, reduced tumor-infiltration of CD8+ T cells and failure to develop tumor-specific CTL." (PMID 24400008, 2013). "Tumor-specific cytotoxic T-cell (CTL) responses in the tumor were significantly enhanced in IL-33-OL-33 wild-type (WT) tumor-bearing (TB) mice but not in IL-33-treated Batf3−/− TB mice." (PMID 37246159, 2023). "Notably, IV BCG-induced tumor-specific response was completely abrogated in Batf3−/− mice, evidenced by dextramer staining and the absence of functional cytotoxicity against B16-F10 tumor cells in vitro." (PMID 37794033, 2023). "To explore the mechanism driving superior tumor control with BATF3 OE, we repeated the in vivo experiment with T cells from two different donors and phenotypically characterized the CAR T cells before treatment and after collecting tumor-infiltrating CAR T cells on day 3 and day 19 post-treatment." (PMID 37945901, 2023). "IL-33-mediated tumor suppression did not occur in Batf3−/− mice." (PMID 37246159, 2023). "Finally, when inoculated on Basic Leucine Zipper ATF‐Like Transcription Factor 3 (Batf3)−/− mice lacking cDC1 cells, the tumor growth disadvantage of Smad4KO PDAC and KPC‐1199 tumors was nearly completely reversed." (PMID 35064757, 2022). "Versikine also enhances the generation of CD103+CD11c+MHCII+ cDCs from Flt3L-mobilized primary bone marrow-derived progenitors, suggesting that Versican proteolysis may promote differentiation of tumor-seeding DC precursors toward IRF8- and BATF3-expressing cDCs in a mouse model." (PMID 36275666, 2022). "Conditional cDC1 depletion prior to tumor implantation failed to phenocopy tumor burden in Batf3–/– mice, highlighting either cDC1-independent defects in Batf3–/– mice and/or insufficient cDC1 depletion in the conditional model, particularly when used with immunotherapies that promote cDC1s." (PMID 35393950, 2022). "Moreover, BATF3 as a T cell receptor is required for dendritic cells to recruit effector CD8 T cells within the tumor environment, and the absence of dendritic cells in β-catenin-expressing tumors results in failed T cell migration into tumors." (PMID 36713370, 2022).
tumor (continued). "Following OV-induced necrosis and pyroptosis of virus-infected tumor cells, tumor antigens attract Batf3 + DCs and scavenging macrophages, resulting in enhanced antigen presentation and subsequent stimulation of specific CD8+ and CD4+ T lymphocytes against the tumor antigen." (PMID 35488303, 2022). "Finally, in vivo experimental results revealed that SETDB1 silencing could impede CRC tumor growth in mice and immune cell infiltration via the FOSB/miR-22/BATF3/PD-L1 axis." (PMID 35497876, 2022). "DMXAA treatment (20 mg/kg i.p., d3 and d7) could attenuate mechanical allodynia or cold allodynia in Batf3−/− mice on d7 and d10 but not d14 after tumor inoculation." (PMID 34315904, 2021). "Notably, the effect of the combination on tumor growth was impaired in Batf3-KO mice, particularly in non-treated tumors, where only the mild effect of CART-gp75 cells was sizeable." (PMID 34810235, 2021). "Interestingly, the infiltration of CD4+ and CD8+ T-cells, but not of NK cells, into the tumor mass depended strongly on BATF3-dependent DCs." (PMID 31188899, 2019). "Recent reports on the Batf3-dependent type 1 conventional DCs (cDC1s) in anti-tumor immunity have greatly advanced our understanding on the interplay of DCs and CD8 T cells in the TME, highlighted by the critical role of CD103+ cDC1s in the cross-priming of tumor antigen-specific CD8 T cells." (PMID 30619378, 2018). "In the absence of this mechanism, (e.g. in tumours with an activated Wnt/β-catenin pathway leading to transcriptional repression of CCL-4), impaired trafficking and function of Batf3+ dependent CD8α+ DCs and a non-inflamed tumour immunophenotype are likely results." (PMID 29157300, 2017). "However, Batf3 was also required to control tumour growth following routes that do not produce Trm, such as i.p. infection with rVACV-OVA and i.d. challenge with B16-OVA cells or following i.p. infection with rVACV-OVA and i.v. challenge with B16-OVA cells." (PMID 28714465, 2017). "To rule out the possibility that circulating memory CD8+ T cells raised in Batf3−/− mice were not functional for anti-tumour immunity, we i.d. infected WT and Batf3−/− mice with rVACV-OVA following OT-I cells transfer, and then transferred purified OT-I Tcm cells to WT recipients." (PMID 28714465, 2017). "Following i.d. challenge with B16-OVA cells, Tcm cell transfer was equally effective in delaying tumour growth irrespective of whether they were generated in WT or in Batf3−/− mice." (PMID 28714465, 2017). "We cannot rule out, however, that the role of Batf3-dependent DCs in generation of Trm13 is also important in the context of tumours or that additional DC subsets may activate Trm34." (PMID 28714465, 2017). "However, the differences in CCL5 and CCL4 expression between IL-32–treated tumors from WT and Batf3–/– mice were not statistically significant, suggesting that DC are not exclusively responsible for the increased tumor chemokine levels in response to IL-32 treatment." (PMID 32841222, 2020). "BATF3 cDC1s (CD8α+ in lymphoid tissues and CD103+ in nonlymphoid ones) were key in mediating MMP2 activity in tumors, as, in their absence, Mmp2-OE tumor growth was reduced." (PMID 34032639, 2021). "As expected, upon femoral inoculation of Batf3+/+ or Batf3−/− mice with LLC cells, only tumor-bearing Batf3+/+ mice but not Batf3−/− mice exhibited a decrease in local tumor burden at d17 following DMXAA treatment." (PMID 34315904, 2021). "Although, in spontaneously rejected tumor grafts, the cellular source of IFN-I was identified as expressing CD11c, IFN-β production was not altered in Batf3−/− mice." (PMID 30809220, 2019). "The absence of Batf3-dependent cross-presenting cDC1s also abolished a significant proportion of the aCD40 anti-tumor effect, underscoring the essential role of cDC1s in initiating CD8 + T cell-mediated tumor immunity." (PMID 40585246, 2025). "In the absence of BATF3 DCs, CD8+ T cells would not migrate to the tumor region." (PMID 37546397, 2023).
tumor (continued). "Indeed, cDC2 are able to cross-present tumor antigens and induce CD4+ T cell responses (including a Th2 phenotype) not relying on BATF3 DCs." (PMID 34032639, 2021). "Indeed, Batf3−/− mice showed impaired rejection of FGL2KO tumors because of significantly reduced CD103+/CD8+ DCs in the brain and TDLNs, showing impairment in initiating the CD8+ T cell response against tumor cells in the absence of Batf3." (PMID 30683885, 2019).
cancer (37 papers, 2015 to 2026). A tumor composed of atypical neoplastic, often pleomorphic cells that invade other tissues. "We found that the significantly activated regulons were involved in T cell biology (RORC, TCF7, NFATC1, and LEF1) or disease pathogenesis (IKZF2 for CD30+ TMF and BATF3 for cALCL) or reported cancer biology (POUZAF1 and TSHZ2)." (PMID 37790936, 2023). "First, we observed that BATF3 OE increased killing of cultured human HER2+ cancer cells by HER2-targeted CAR T cells across donors and effector:target (E:T) ratios." (PMID 37945901, 2023). "The importance of IFN-β production by cancer cells in the recruitment and activation of Batf3-dependent dendritic cells has been also demonstrated in different settings." (PMID 36949064, 2023). "Batf3-/- mice lack cDC1 cells, and cancers evolving in such mice fail to respond to PD-1 blockade or other types of immunotherapies." (PMID 37623817, 2023). "BATF3 overexpression counteracts T cell exhaustion and enhances cancer immunotherapy in in vivo models." (PMID 37945901, 2023). "Although we found that knocking down the expression of BATF3 will increase cancer’s sensitivity to cisplatin, the main function of this transcription factor is to activate CD8alpha+ dendritic cells." (PMID 35410350, 2022). "In particular, activation of STING signaling in the DCs lineage driven by the basic leucine zipper transcription factor ATF-like 3 (BATF3) is a central step in the overall cancer immune cycle." (PMID 35046953, 2021). "Necrotic cancer cells are commonly engulfed by antigen-presenting cells, especially the basic leucine zipper transcription factor ATF-like 3 (BATF3)-driven lineage of dendritic cells (DCs)." (PMID 32854711, 2020). "Intriguingly, after transplantation of BATF3-transduced B cells, all 14 transplanted animals developed malignancies with a latency of 56-213 days." (PMID 29662618, 2018). "Some of LINC00094 target PCGs have well‐known functions in cancer, including BATF3, SCG2, and MCM2." (PMID 32460441, 2020). "In addition, the authors suggest that both cytosolic DNA sensing and Batf3-dependent CD103+/CD8α+ DCs are essential to the antitumor efficacy of this mode of cancer immunotherapy." (PMID 30626434, 2019). "Although mice deficient in BATF3 and lacking cDC1s display severe defects in T cell responses to tumors, this is likely not solely due to defective XP but to loss of additional cDC1 and T cell functions in cancer immunity." (PMID 41482545, 2026). "Second, we focused on BATF3 which encodes a chromatin remodeling protein that also cooperates with IRF proteins and that promotes CD8+ T cell survival and memory differentiation, to the extent that it has been proposed to optimize cells used in cancer immunotherapy." (PMID 38055824, 2023). "Indeed, in most mouse and human cancers, the presence of immune cells, such as cytotoxic T cells and DCs (in particular, the Batf3-dependent CD103+ sub-type), or of inflammatory mediators, such as type I interferons (IFNs), IFN-γ, and IL-12, is associated with good prognosis." (PMID 26343581, 2015). "DCs, especially the Batf3-dependent sub-family characterized by CD8α and/or CD103 expression, are essential for anti-cancer immune responses." (PMID 26343581, 2015). "As an orthogonal method of inducing T cell exhaustion, we acutely or chronically stimulated HER2-targeted CAR T cells with or without BATF3 OE with HER2+ cancer cells." (PMID 37945901, 2023). "Among these genes, only BATF3 and IRF4 were highly co-expressed with BATF in the majority of cancers, which suggested that BATF might carry out its role by cooperating with BATF3 and IRF4." (PMID 35573731, 2022). "The model we created and based on the expression of 3 genes, BATF3, IRF5, ZBTB38, could help in the prediction of the reaction and prognosis of cancer patients given platinum-based, especially cisplatin-including chemotherapies." (PMID 35410350, 2022).
cancer (continued). "In mice, knockout of BATF3 results in more metastases in a NK cell-dependent manner and regulates the activity of Th17 through IL-12 production though this regulation was not demonstrated in the context of cancer." (PMID 38750495, 2024). "Moreover, cancers evolving in Batf3-/- mice do not respond to PD-1 blockade or other types of immunotherapy." (PMID 37623817, 2023). "Moreover, BATF3 can influence the apoptosis and longevity of T cells via the proapoptotic factor BIM, indicating that BATF3 has the potential to optimize adoptive T-cell therapy (ACT) in cancer patients." (PMID 36248886, 2022). "For example, the increased expression of Basic Leucine Zipper ATF-Like Transcription Factor 3 (BATF3) mediated by the JAK-STAT signaling pathway can result in the activation of MYC, which can affect the proliferation and apoptosis of cells and contribute to the formation of cancer." (PMID 35406421, 2022).